BIRC5 (baculoviral IAP repeat containing 5)
Diseases named in the same sentence as BIRC5 in open-access papers (continued):
Sharing a sentence is not in itself a finding about the gene and the disease.
neurodegenerative disease (1 paper, 2025). A disorder of the central nervous system characterized by gradual and progressive loss of neural tissue and neurologic function. "Changes in BIRC5 expression are closely linked to neuronal apoptosis, with reduced expression leading to increased neuronal apoptosis, memory dysfunction, and the progression of neurodegenerative diseases." (PMID 40896707, 2025).
BIRC5 also shares sentences with these, for which no sentence is quoted: nasopharyngeal carcinoma (5 papers); invasive breast carcinoma (4); malignant glioma (4); multiple myeloma (4); breast (2); clear-cell renal cell carcinoma (2); Ductal carcinoma in situ (2); malignant peripheral nerve sheath tumor (2); metastatic prostate carcinoma (2); ovarian serous cystadenocarcinoma (2); papillary renal cell carcinoma (2); pulmonary arterial hypertension (2); thyroid (2); acute pancreatitis (1); alcoholism (1); Alport syndrome (1); Alzheimer disease (1); amyotrophic lateral sclerosis (1); Apert syndrome (1); benign meningioma (1); bladder urothelial carcinoma (1); Burkitt lymphoma (1); carcinoma in situ (1); chronic kidney disease (1); clear cell carcinoma (1); colorectal tumors (1); cyst (1); dengue fever (1); dysplasia (1); emphysema (1).
A further 43 diseases each share a sentence with BIRC5 in 1 paper.